IL27 (interleukin 27)
Diseases named in the same sentence as IL27 in open-access papers (continued):
Sharing a sentence is not in itself a finding about the gene and the disease.
COVID-19 (39 papers, 2020 to 2025). A disease caused by infection with severe acute respiratory syndrome coronavirus 2. "IL-27, among other cytokines, is deeply involved in immune-mediated processes associated with COVID-19." (PMID 39063193, 2024). "Here, we measured the expression of mRNA encoding IFNs and IL27 subunits in PBMCs and monocytes from COVID-19 patients." (PMID 37310504, 2023). "mRNAs encoding interleukin 27 subunits are strongly induced in PBMCs and monocytes from COVID-19 patients and are associated with disease severity." (PMID 37310504, 2023). "Consistent with prior reports, IL-6, well-known to associate with poor survival during COVID-19, IL-27, and IL-15 were also observed to stratify survival, but IL-6 displayed a lower hazard ratio than IL-18." (PMID 36894537, 2023). "Levels of four cytokines (IL-6, IL-10, IL-18, IL-27) were consistently elevated in patients with COVID-19 independently of the variant." (PMID 36430621, 2022). "For IL-27, however, concentrations in patients with acute COVID-19 were significantly higher independently of the variant." (PMID 36430621, 2022). "The inflammatory cytokine profile of Pso patients at risk for COVID-19 included in our study showed increased levels of IL-18, IL-17A and IL-6 and decreased levels of IL-27 when compared to HCs." (PMID 34068473, 2021). "However, as we delved further into the investigation of IL-27 and its involvement in COVID-19, we also analyzed the correlation between IL-27 and the SARS-CoV-2 genetic variant." (PMID 39063193, 2024). "In addition to our previous studies on the role of cytokines in COVID-19, we conducted another investigation to explore the association between IL-27 blood plasma concentrations and disease outcome." (PMID 39063193, 2024). "Indeed, it has been reported that decreased IL-27 serum levels are associated with severe COVID-19 and fatalities." (PMID 39194742, 2024). "Importantly, we noted that the levels of mRNA encoding IL27p28 and EBI3, i.e., both IL27 subunits, increased significantly with the severity of COVID-19." (PMID 37310504, 2023). "Serum from patients with severe COVID-19 induced increased levels of IL-1α, IL-1Ra, IL-5, IL-6, IL-10, IL-12(p40), IL-18, IL-27, and TNF-α." (PMID 41583455, 2025). "Upon comparing acute-phase COVID-19 patients with healthy donors, we observed a statistically significant increase in IL-27 plasma levels in acute COVID-19 patients." (PMID 39063193, 2024). "We believe IL-27 to be a potential key player in the development of COVID-19 and protection against it." (PMID 39063193, 2024). "Another study used machine learning to predict the outcome of COVID-19 and identified a few cytokines, including IL-27, IL-9, IL-12p40, and monocyte-chemotactic protein 3 (MCP-3), as potential indicators for mild cases of the disease." (PMID 39063193, 2024). "Within this study, we will explore the role of IL-27 in immune responses and analyze both the existing literature and our own prior research findings on this cytokine in the context of COVID-19." (PMID 39063193, 2024). "One such cytokine is interleukin 27 (IL-27), which has been found to be elevated in the blood plasma of patients with COVID-19." (PMID 39063193, 2024). "Cytokines, such as IL1A and IL27, which have been shown to be higher in patients with more severe COVID-19 disease, were highly expressed in COVID-19(+) TV skin in comparison to the other groups." (PMID 37026002, 2023). "LDA model 2 identified IL-27 and IP-10 as the top two predictors of clinical deterioration in COVID-19." (PMID 37731491, 2023). "Our literature review on COVID-19/SARS-CoV-2 revealed a gap in knowledge regarding the potential involvement of IL27 in the induction of ISG expression." (PMID 37310504, 2023). "Cytokine production and signaling (including FFAR3 and IL27) was significantly increased in COVID-19, most markedly at T1 and T2." (PMID 37365222, 2023).
COVID-19 (continued). "IL-27 is involved in the development of Th1 cells and is a reliable predictive biomarker for COVID-19." (PMID 37015978, 2023). "We found that pro-inflammatory and inflammatory chemokines, such as IL-17, IL-23 and IL-27, were increased in COVID-19-positive patients compared with their healthy controls." (PMID 37112613, 2023). "Both PBMCs and monocytes from COVID-19 patients classified according to their severity express high levels of the two subunits of IL27, which is dependent on the severity of the disease." (PMID 37310504, 2023). "While IL27 was significantly reduced in severe COVID-19 patients who required intensive care, the IL27 level was significantly higher in severe COVID-19 survivors." (PMID 37310504, 2023). "The data suggest a link between IL27 and certain TLRs and disease progression in patients with COVID-19." (PMID 37310504, 2023). "We found that the expression of TLR2 increased with the severity of COVID-19 in both PBMCs and monocytes (respectively), similar to what was observed with IL27 subunits." (PMID 37310504, 2023). "Based on these observations, together with our results showing a correlation with the severity of the disease, we propose that IL27 can be a useful marker of COVID-19 disease progression." (PMID 37310504, 2023). "In agreement with our transcriptomic analysis, other studies described high levels of IL27 in COVID-19 patients." (PMID 37310504, 2023). "We found that Th1-type cytokines IL-18 and IL-27 were increased in the patient with COVID-19 vaccine-related myopericarditis compared to both healthy and vaccine control groups." (PMID 35251049, 2022). "Increases in IL-12p40, IL-12p70, IL-15 and IL-27 in severe COVID-19 patients have previously been described." (PMID 36142255, 2022). "IL-18 and IL-27, Th1-type cytokines, were highly increased in the patient with COVID-19 vaccine-related myopericarditis compared with vaccinated controls who experienced no cardiac complications." (PMID 35251049, 2022). "In this regard, we hereby report that HGF, IL1α, and IL27 contribute to the deterioration of the disease and the adverse outcome of COVID-19 revealing these three compounds as novel biomarkers but as future therapeutic targets in COVID-19." (PMID 34066892, 2021). "We have also found how low level of IL-27, which belongs to the IL-12 family and is therefore involved in Th1 differentiation, is a good prognosis biomarker in COVID-19 patients." (PMID 34066892, 2021). "We are open to discussing this topic further and welcome any insights or perspectives that may help us better understand the role of IL-27 and other cytokines in COVID-19." (PMID 39063193, 2024). "And even though its full role in the immune responses behind COVID-19 is yet to be explored, it is now clear that IL-27 may be one of the most interesting cytokines involved in this infection." (PMID 39063193, 2024). "Here, we investigated transcription levels of both IL27 subunits in COVID-19 patients." (PMID 37310504, 2023). "Collectively, the data suggest that an increase in IL27 expression correlated with COVID-19 severity, indicating that IL27 might be a marker of the antiviral response to SARS-CoV-2 infection or a possible biomarker of COVID-19 progression." (PMID 37310504, 2023). "Thus, PBMCs from COVID-19 patients in critical condition or monocytes from COVID-19 patients in severe condition showed the highest expression levels of the two IL27 subunits." (PMID 37310504, 2023). "By contrast, low levels of IL27 have been reported in COVID-19 patients at admission." (PMID 37310504, 2023). "In the current study, we report that the levels of TLR1/2-MyD88 signaling components, the NF-κB complex, and IRF1 were significantly increased as a function of the severity of COVID-19, and the results were consistent with expression levels of IL27 subunits in COVID-19 patients." (PMID 37310504, 2023).
COVID-19 (continued). "The level of mRNA encoding STAT1 and STAT3 is elevated in COVID-19 patients, regardless of disease severity, and the results suggest that IL27 signaling is activated in response to SARS-CoV-2 infection." (PMID 37310504, 2023). "Another study of COVID-19 patients also found an increase in IL27 production." (PMID 37310504, 2023). "Marked elevation of IL-27 was reported in a single case of mRNA-1273 COVID-19 vaccine-related myocarditis, with more moderate increases in IL-27 in recently vaccinated control individuals (incidentally, inflammasome activation was also implicated in the vaccine-related myocarditis)." (PMID 36148243, 2022). "Low serum levels of IL-27 have been described as a good prognosis indicator for adult COVID-19, and the up-regulation of this gene in our cohort suggests that IL-27 may be a key undescribed contributor to MIS-C phenotypes after SARS-CoV-2 exposure in children." (PMID 36096831, 2022). "At the beginning, there was an increased serum IL-27 level noted in patients with acute COVID-19 compared to COVID-19 convalescents and healthy controls (4533 ng/mL (2494; 7144) vs. 1422 ng/mL (1081; 1699) and 966 ng/mL (733; 1944), respectively, p < 0.001 in both cases)." (PMID 36146713, 2022). "It has been suggested that low levels of IL-27 could be a promising biomarker for COVID-19 prognosis." (PMID 35782361, 2022). "Therefore, the early detection of HGF, IL-1α, and IL27 plasma levels in patients in COVID-19 patients can provide useful information for getting quickly intensive treatment as well as providing possible therapeutic targets." (PMID 34066892, 2021). "However, the four cytokines (IL-6, IL-10, IL-18, and IL-27) that were consistently elevated in COVID-19 patients may provide valuable insights into the equilibrium behind disease progression and host infection." (PMID 39063193, 2024). "The 2023 publication authored by Valdés-López and Urcuqui-Inchima revealed that the identification of mRNA encoding IL-27 subunits in peripheral blood mononuclear cells (PBMCs) and monocytes from individuals with COVID-19 was linked to the severity of the disease." (PMID 39063193, 2024). "Next, we investigated whether IL27 was positively correlated with COVID-19 severity." (PMID 37310504, 2023). "Finally, IL-27 negatively correlated with the CCR6+ cells in acute COVID-19 patients." (PMID 36146713, 2022). "Therefore, regulating the CCR6+CD8+T cell subset is a crucial aspect of COVID-19, whereas IL-27 might act as a potential regulator thereof." (PMID 36146713, 2022). "Thus, circulating NK cells and T cells might be activated directly by elevated IL-18 and IL-27 in the patient with COVID-19 vaccine-related myopericarditis." (PMID 35251049, 2022). "During SARS-CoV-2 infection, monocytes and macrophages detect viral particles and produce IL-6, IL-1β, and IFN-π/IL-27 through TLR, NF-κB activation, and inflammasome assembly, contributing to acute respiratory distress syndrome (ARDS) and severe COVID-19." (PMID 40934228, 2025). "The seven pro-inflammatory cytokines (IL-6, IL-8, IL-15, IL-18, IL-27, IFN-γ, and TNF-α) and two anti-inflammatory cytokines (IL-1RA and IL-10) were elevated in COVID-19 patients compared to healthy controls." (PMID 39408907, 2024). "Transcriptomic analysis showed that the expression of both IL27 subunits – IL27p28 and EBI3 – increased with severity of COVID-19 in both PBMCs and monocytes (respectively)." (PMID 37310504, 2023). "The present data indicate that DPSC administration might be effective in patients with COVID-19-induced hyper-inflammation, due to the inhibition in the production of several cytokines by activated T lymphocytes, namely, IFNγ, TNFα, IL-2, IL-9, IL-10, IL-17A, IL-18, IL-21, and IL-27." (PMID 33634100, 2020). "Notably, convalescent serum showed significant decreases in sICAM-1, sVCAM-1, P-selectin, IL-1α, IL-1ra, IL-10, IL-27, TNF-α, TGF-α, and G-CSF compared to serum from severe COVID-19 patients." (PMID 41583455, 2025).
COVID-19 (continued). "The results suggest that IL27 induces a robust STAT1-dependent pro-inflammatory and antiviral response in an IFN-independent manner in COVID-derived PBMCs and monocytes as a function of a severe clinical course of COVID-19." (PMID 37310504, 2023). "IL-27, IL-17A and IL-12 plasma levels increased in COVID-19 non-HD patients depending on disease severity, whereas no significant dynamics were detected in HD patients." (PMID 35265078, 2022). "Our results show that the levels of IL-12p70 are significantly increased in severe COVID-19 survivors compared to non-survivors, as are those of IL-12p40, IL-15 and IL-27." (PMID 36142255, 2022). "On the contrary, taking into account anti-inflammatory cytokines, IL-1RA, IL-10, IL-27, and IL-19 were higher in COVID-19 pregnant women if compared with noninfected ones." (PMID 34326336, 2021). "Despite immune deviations and lower IL-27, which has a potential antiviral impact, psoriatic patients did not exhibit complications related to COVID-19." (PMID 34068473, 2021). "COVID-19 is also characterized by a “cytokine storm” with increased levels of pro-inflammatory cytokines in the blood, such as IL-1β, TNF-α, IL-6, IL-12, and we detected increased IL-1β, IL-6, IL-12, IL-23, and IL-27 in the serum following ORN06 aspiration." (PMID 33481950, 2021). "First, we studied the circulating levels of IL-1α, IL-1β, IL-18, IL-15, IL-12p40, IL-12p70, IL-6, IL-27, IL-1Ra, IL-1RI, IL-1RII, IL-6R and sgp130, which are innate proinflammatory cytokines, and their receptors in survivors and non-survivors of severe COVID-19 and healthy controls." (PMID 36142255, 2022). "Moreover, serum IL-27 levels also showed a negative correlation with the absolute numbers of central memory and terminally differentiated effector memory cells (Tc17 cells) from patients with acute COVID-19 but not from convalescent or healthy donors." (PMID 39063193, 2024). "Negative correlations found between Tc17 subsets and serum IL-27 levels revealed in our study during acute COVID-19 may suggest suppressed cytokine-producing Tc17 potential and CD8+ T cell differentiation skewed towards Tc1 as the most crucial cell type in eliminating intracellular pathogens." (PMID 36146713, 2022). "Indeed, defined circulating factors - CXCL8, IL-10, IL-15, IL-27, and TNF-α - positively correlate with older age, longer hospitalization, and a more severe form of the disease and may thus represent the leading signature in critical COVID-19 patients." (PMID 33159040, 2020). "IL-27, IL-9, IL-12p40, and MCP-3 seemed significant in non-Severe samples, and other studies have reported aberrant levels of these cytokines in COVID-19 patients." (PMID 37015978, 2023). "Also, patients with COVID-19 were characterized by increased secretion of proinflammatory cytokines CCL20/MIP3ɑ, IL-10, IL-15, IL-27 in non-survivors than in controls." (PMID 36758022, 2023). "The interleukin genes IL1RN and IL27 were only upregulated in G2; however, IL6 was not upregulated in either group, corroborating previous observations in lung tissue, despite high levels in the blood of COVID-19 patients." (PMID 35438176, 2022). "Interestingly, TNFα, IL-27, IL-17A and IL-12 plasma levels of SARS-CoV-2 negative HD patients were in a similar range as in moderate and severe COVID-19 non-HD patients." (PMID 35265078, 2022). "Next, we found that IL-27 negatively correlated with the CCR6+CD8+ T cell frequencies within EM (r = –0.400, p = 0.006) and TEMRA (r = –0.343, p = 0.021) subsets in patients with acute COVID-19, but not in convalescents COVID-19 or healthy controls (respectively)." (PMID 36146713, 2022).
rheumatoid arthritis (37 papers, 2008 to 2025). A chronic, systemic autoimmune disorder characterized by inflammation in the synovial membranes and articular surfaces. "Injections of IL-27 cause disease improvement when injected in a murine model of rheumatoid arthritis." (PMID 39063193, 2024). "Previous studies have demonstrated the association of rheumatoid arthritis with the increase in IL-27 levels in serum, synovial membranes, and synovial fluid." (PMID 33312724, 2020). "In murine models of collagen-induced arthritis, researchers observed that IL-27 was expressed in rheumatoid arthritis synovial membranes and that ectopic IL-27 expression decreased disease severity compared to that in untreated control mice." (PMID 36028492, 2022). "IL-27 levels are generally elevated in blood, synovial fluids, synovial fibroblasts, and even rheumatoid nodules." (PMID 35058928, 2021). "Elevated levels of IL‐6 and IL‐27 have been observed in chronic inflammatory conditions, such as rheumatoid arthritis and a lot of hematopoietic malignancies and solid tumours." (PMID 33277798, 2021). "Although increased levels of this cytokine were reported in patients with rheumatoid arthritis compared to healthy subjects, the role of IL-27 is complex and in addition to anti-inflammatory activity, its pro-inflammatory function should be considered." (PMID 34033291, 2021). "Previous studies found that IL-27 levels are elevated in RA blood, synovial fluid, and rheumatoid nodules." (PMID 35058928, 2021). "Altered concentrations of IL-27 have been shown in various auto-immune diseases such as multiple sclerosis, rheumatoid arthritis, and psoriasis." (PMID 32616337, 2020). "It has been reported that IL-27 is elevated in patients with autoimmune/inflammatory diseases such as Crohn’s disease, rheumatoid arthritis, multiple sclerosis, psoriasis, and aplastic anemia." (PMID 31835347, 2019). "In patients with rheumatoid arthritis, synovial IL-27 expression inversely correlates with development of ectopic lymphoid-like structures." (PMID 30736372, 2019). "In this line, interleukin-27 (IL-27) modulates inflammation and can be produced directly at inflammatory sites such as in the joints during rheumatoid arthritis or in the central nervous system (CNS) during MS." (PMID 28738904, 2017). "Elevated expression of IL-27 has been detected in the synovial membranes and fluid of rheumatoid arthritis (RA)." (PMID 20604932, 2010). "In rheumatoid arthritis, IL-27-MSC may alleviate joint inflammation by suppressing Th17 activation and promoting Treg expansion, while TSG-6 protects articular cartilage through inhibition of hyaluronan degradation." (PMID 40642057, 2025). "In rheumatoid arthritis, IL-27 is often found in the synovial tissue of affected joints." (PMID 39063193, 2024). "Further studies should keep exploring the level of IL-27 in rheumatoid nodules and whether IL-27 from rheumatoid nodules contributes to sustained systemic and synovial inflammation." (PMID 35058928, 2021). "We determined whether there is aberrant expression of interleukin-27 (IL-27) in rheumatoid arthritis (RA) patients and investigated the clinical significance of these changes." (PMID 27869736, 2016). "Through evaluation of synovial tissues from rheumatoid arthritis patients it has been recently reported that low interleukin-27 (IL-27) expression corresponds with an increased incidence of TLO and gene signatures associated with their development and activity." (PMID 28082981, 2016). "We and others have previously shown that IL-27 is expressed at high levels in various Th1 and/or chronic inflammatory conditions such as tuberculosis, sarcoidosis, inflammatory bowel diseases, visceral leishmaniasis, and rheumatoid arthritis." (PMID 24130734, 2013).